FGF21 (fibroblast growth factor 21)
Diseases named in the same sentence as FGF21 in open-access papers (continued):
Sharing a sentence is not in itself a finding about the gene and the disease.
Obesity (continued). "In our results, the induction of the mRNA levels of adiponectin, FgfR1, FgfR4 and Egr1 in scWAT of HFDM mice indicates that, in obesity, maqui supplementation increases the sensitivity to FGF21 of scWAT." (PMID 31480627, 2019). "Studies have shown that FGF21 levels are positively correlated with obesity and hepatic steatosis degree." (PMID 30927227, 2019). "Administration of FGF21-mimetic antibody treats diabetes and obesity FGF21 by lowering blood glucose levels and enhancing insulin sensitivity in diabetic." (PMID 30842736, 2019). "Fgf21 has recently emerged as a potential therapeutic target for treating obesity and type 2 diabetes." (PMID 31736786, 2019). "The study also showed that spurious activation of PERK increases the gene expression and secretion of fibroblast growth factor 21 (FGF21), an anti-obesity factor which stimulates energy expenditure in brown adipose tissue." (PMID 31817027, 2019). "Several studies have found FGF-21 levels are correlated with BMI, waist circumference and visceral adipose tissues, suggesting that obesity is an FGF-21 resistant state." (PMID 31817052, 2019). "Consistent with the mice studies, the administration of FGF21 analog shows good performance in patients with obesity and T2D." (PMID 31736870, 2019). "As per a clinical study, advancements were preliminarily obtained in patients with obesity which ameliorates dyslipidemia by applying FGF21 analogues." (PMID 31498116, 2019). "As a potent metabolic regulator, FGF21 has been closely related to obesity-related disorders, such as hyperglycemia, dyslipidemia, insulin resistance, and hepatosteatosis." (PMID 31205953, 2019). "With regards to FGF21, our study confirmed the findings that FGF21 is induced in obesity through nutritional deprivation and through a high-fat diet, in nonhuman primates." (PMID 31405194, 2019). "FGF21 is known to regulate insulin sensitivity and body weight, and circulating serum FGF21 concentration increases as a result of FGF21 resistance in obesity and diabetes." (PMID 31323977, 2019). "Obesity is a state in which circulating levels of FGF21 are elevated in obese mice, in rhesus monkeys fed a HFD, and in the serum of overweight/obese humans." (PMID 31546675, 2019). "FGF21 is also elevated in pathological conditions, such as obesity, insulin resistance, or liver diseases, and impairment in FGF21 signaling in these cases has also been described." (PMID 31546675, 2019). "In recent years, FGF21 has emerged as a potential candidate for treatment of obesity and type II diabetes." (PMID 30688648, 2019). "Recently, relationships between higher FGF-21 levels and adverse lipid profiles, obesity, metabolic syndrome, or type 2 diabetes mellitus have been reported in adults." (PMID 31750276, 2019). "This is consistent with HFD increasing body mass and inflammation whereas pLPHC diet upregulates FGF21 to decrease obesity and insulin resistance." (PMID 31019501, 2019). "FGF21 has been actively assessed for its therapeutic potential to treat metabolic disease due to its success in counteracting obesity in several different animal models." (PMID 30813227, 2019). "The Fibroblast Growth Factor 21 (FGF21) is considered an attractive therapeutic target for obesity and obesity-related disorders due to its beneficial effects in lipid and carbohydrate metabolism." (PMID 31546675, 2019). "A positive correlation between FGF21 levels and obesity-related parameters such as WC, waist-to-hip ratio, BMI, and body fat percentage were found even after adjusting for age." (PMID 31582974, 2019). "Additionally, serum levels of FGF21 were associated with metabolic parameters, including BMI, serum glucose levels, and serum TG levels, suggesting that FGF21 may mediate the association between obesity and tumor progression in PTC." (PMID 31408968, 2019).
Obesity (continued). "Although FGF21 is considered as a therapeutic target in obesity-related metabolic disorders, the potential of FGF21 to control the atrophy of skeletal muscle in obese conditions is unclear." (PMID 31312114, 2019). "Although FGF21 performs several beneficial functions, its serum level is known to be increased in obesity and diabetes, suggesting a potential FGF21-resistant state." (PMID 31543863, 2019). "Some of the described FGF21 analogues or activators are classified as anti-obesity and antidiabetic molecules that improve insulin sensitivity, ameliorate hepatosteatosis, and promote weight loss." (PMID 31546675, 2019). "In metabolic disorders such as obesity and type 2 diabetes (T2D), high levels of FGF21 are thought to represent compensatory responses to maintain metabolic homeostasis, which also represents its resistant state." (PMID 31511499, 2019). "Pharmacological studies have demonstrated that FGF21 improves insulin sensitivity, thereby countering the development of metabolic diseases, including obesity and T2DM." (PMID 31121855, 2019). "FGF21 is paradoxically increased in insulin-resistant states such as obesity or type 2 diabetes; this suggests either a resistance to FGF21 effects or a compensatory response to these metabolic disarrangements." (PMID 30804796, 2019). "FGF21 boosts glucose uptake, decreases hepatic gluconeogenesis, increases insulin sensitivity and lessens hyperglycemia in a diet-induced mouse model of obesity." (PMID 29444136, 2018). "This situation is comparable to the FGF21 resistance status observed in obesity and type 2 diabetes." (PMID 29661866, 2018). "Nonetheless, the plasma concentration of FGF21 is also known to be elevated under conditions of metabolic dysfunction, such as obesity." (PMID 30211220, 2018). "It was shown previously that Bet supplementation stimulates hepatic and circulating Fgf21 levels and improves FA oxidation and energy balance in rodent models of diet induced obesity." (PMID 30042948, 2018). "Paradoxically, muscle- or liver-specific knockout of the Atg7 gene protected mice from obesity and insulin resistance by upregulating the expression of fibroblast growth factor (FGF21)." (PMID 30116482, 2018). "Long-term administration of FGF21 analogs can improve dyslipidemia and decrease body weight in patients with obesity and type 2 diabetes (T2DM)." (PMID 29348470, 2018). "Pre-clinical evidence of FGF21’s potential role in metabolism includes resistance to diet induced obesity in mice overexpressing FGF21 and improved glucose tolerance in obese mice through administration of recombinant FGF21." (PMID 29641994, 2018). "Our results show that FGF21 gene therapy holds great translational potential in the fight against insulin resistance, T2D, obesity, and related comorbidities." (PMID 29987000, 2018). "Despite its multiple benefits, FGF21 is paradoxically elevated in obesity and diabetes in both animals and humans." (PMID 29348470, 2018). "Fibroblast growth factor 21 (FGF21) has recently emerged as a promising therapeutic agent for the treatment of obesity and T2D." (PMID 29987000, 2018). "FGF21 acts on lipid metabolism and weight, is negatively regulated by LXR, and induces secretion of the obesity-associated adipokine, Adiponectin27,31,51." (PMID 29899496, 2018). "FGF-21 can stimulate glucose uptake, lower blood glucose and lipid levels, and ameliorate several metabolic perturbations in obesity and type 2 diabetes mellitus (T2DM)." (PMID 30298107, 2018). "Recent studies show that the FGF21 agonist is a promising therapeutic agent for the treatment of type 2 diabetes and obesity." (PMID 29949887, 2018). "FGF21 has diverse metabolic effects that are beneficial for managing obesity, increasing fatty acid oxidation in the liver, and improving insulin sensitivity in obese individuals." (PMID 30275865, 2018).
Obesity (continued). "The administration of FGF21 reverses hepatic steatosis, prevents diet-induced obesity, and alleviates insulin resistance and dyslipidemia." (PMID 30355361, 2018). "Taken together, this result further demonstrates that elevation of FGF21 in circulation and its action on adipose tissue lead to the accumulation of subcutaneous fat mass in diet-induced obesity." (PMID 29348470, 2018). "Meanwhile, GK rats in our study had FGF21 levels between 320 and 460 pg/mL, which is consistent with the elevated levels observed in individuals with obesity and diabetes, and in other animal models of diabetes." (PMID 29593555, 2018). "The present work provides the first evidence of long‐term counteraction of obesity and insulin resistance upon a one‐time administration of a gene therapy AAV vector encoding FGF21." (PMID 29987000, 2018). "Unexpectedly, we found elevated endogenous FGF21 in obesity serves as a defense mechanism against systemic insulin resistance." (PMID 29348470, 2018). "Pharmacologically, recombinant FGF21 as a therapeutic intervention was reported to reduce obesity, as well as adiposity, hyperglycemia, and hyperinsulinemia, in both rodents and nonhuman primates." (PMID 30157856, 2018). "Data showed the autocrine/paracrine “positive feedback” loop effect: FGF21 autostimulated the FGF21 production and its secretion from cardiomyocytes in response to obesity and hypoxia." (PMID 30671457, 2018). "FGF21 transgenic mice fed high -fat/high -carbohydrate diet for 15 weeks showed protection against diet-induced obesity, and FGF21 knockout (KO) mice developed more severe steatosis and fibrosis than wild- type mice." (PMID 29444136, 2018). "Surely, FGF21 treatment reduces body weight and improves glucose metabolism in mouse models of obesity and diabetes." (PMID 30041488, 2018). "There is still much to discover regarding FGF21 action but consideration of the points outlined here can help avoid ambiguity in defining “FGF21 resistance” during obesity." (PMID 29983922, 2018). "Indeed, first‐generation FGF21 analogues have already reached the clinical stage, and reports from two phase I clinical trials have shown significant improvement of dyslipidemia, slight body weight loss, and reductions in fasting insulinemia in patients with obesity and T2D." (PMID 29987000, 2018). "This scenario, which is reminiscent of “FGF21 resistance,” is analogous to the situation found in obesity and type 2 diabetes." (PMID 29661866, 2018). "Unexpectedly, levels of circulating FGF-21 have been found to be higher in people with obesity, T2DM, and NAFLD, when compared to normal individuals." (PMID 30298107, 2018). "FGF21, as a potential therapeutic for metabolic disease, such as diabetes and obesity, can increase thermogenesis." (PMID 29295856, 2018). "FGF21 has also been reported to reduce blood glucose levels and improve insulin sensitivity under some pathological conditions, such as obesity and diabetes, by promoting thermogenesis and browning of white adipose tissue (WAT)." (PMID 29593555, 2018). "However, since the metabolic phenotypes observed in Wy-HFD were alleviated in Wy-FGF21-KO, we speculated that Fgf21 through DNA demethylation induced during the suckling period may be at least in part associated with the attenuation of diet-induced obesity in adulthood." (PMID 29434210, 2018). "Our study underscores the potential of FGF21 gene therapy to treat obesity, insulin resistance, and T2D." (PMID 29987000, 2018). "Obesity is accompanied by FGF21 resistance, both in the periphery and in the brain, due to receptor downregulation and reduced FGF21 transfer to cerebrospinal fluid." (PMID 30389922, 2018). "Our results constitute the basis to support the future clinical translation of FGF21 gene transfer to treat T2D, obesity, and related comorbidities." (PMID 29987000, 2018). "The induction of FGF21 by CO attenuated endoreticulum stress- or diet-induced, obesity-dependent hepatic steatosis." (PMID 29295856, 2018).
Obesity (continued). "Fibroblast growth factor 21 (FGF21) has recently attracted great attention due to its multiple therapeutic benefits against obesity-related medical complications." (PMID 29348470, 2018). "Administration of exogenous FGF-21 ameliorates several physiological perturbations related to metabolic diseases in animal models of obesity and diabetes." (PMID 30298107, 2018). "FGF21 has favorable effects in several metabolic diseases including type 2 diabetes, dyslipidemia, and obesity." (PMID 30275865, 2018). "In the case of FGF-21, high plasma levels and resistance to its effects have been documented in rodent models of obesity and diabetes." (PMID 29445355, 2018). "Taken together, our work provides evidence that elevated endogenous FGF21 in obesity serves as a defense mechanism against systemic insulin resistance." (PMID 29348470, 2018). "Paradoxical to these beneficial metabolic effects, circulating FGF21 is increased during obesity potentially suggesting a state of “FGF21 resistance”3." (PMID 29983922, 2018). "Fgf21 stimulates lipolysis by a systemic release of catecholamines and is critical for attenuation of obesity." (PMID 30042948, 2018). "Replenishment of recombinant FGF21 to a level equivalent to that in obesity restores SAT mass and reverses insulin resistance in FGF21KO, but not in adipose-specific βklotho knockout mice." (PMID 29348470, 2018). "Circulating levels of FGF21, a potent insulin sensitizer and metabolism regulator, are elevated in mouse models of obesity although obese mice still respond to high doses of FGF21 by ameliorating glucose and lipid parameters (reviewed in20)." (PMID 30374109, 2018). "In this work, we have developed gene therapy approaches for obesity and insulin resistance based on the use of AAV vectors encoding FGF21." (PMID 29987000, 2018). "Of note, a recent study showed by using adipocyte‐specific β‐klotho (Klb) receptor knockout mice that BAT mediates the glucose‐lowering effect of FGF21, whereas the anti‐obesity effect of FGF21 appears to be through non‐adipose tissues." (PMID 30021799, 2018). "These FGF21‐class molecules have been reported to have similar therapeutic efficacy than the native FGF21 protein in small and large animal models of obesity and T2D." (PMID 29987000, 2018). "The level of FGF21 in serum has been found to be elevated in several metabolic disorders related to obesity." (PMID 29444136, 2018). "As a novel adipokine, FGF21 plays a critical role in cardio-metabolic diseases, including obesity, diabetes, and cardiovascular diseases." (PMID 30185439, 2018). "We propose that elevated levels of endogenous FGF21 in obesity serve as a defense mechanism to protect against systemic insulin resistance." (PMID 29348470, 2018). "FGF21 treatment of mice was shown to correct obesity and to improve insulin sensitivity and glucose control in rodents and humans." (PMID 30547786, 2018). "We next performed a high fat diet (HFD) feeding time course to identify when eWAT KLB protein levels decrease in relation to increased plasma FGF21 levels during the development of obesity." (PMID 28580290, 2017). "PPARα also induces expression of Fibroblast Growth Factor 21 (FGF21), a hepatocyte-derived hormone suppressing obesity-induced fatty liver." (PMID 29286303, 2017). "We found that the depletion of hepatic Crtc2 is beneficial in relieving not only hyperglycemia but also improving whole-body energy metabolism in diet-induced obesity (DIO) mouse models by promoting an Fgf21-dependent pathway." (PMID 29192248, 2017). "The beneficial effects of FGF21 on body weight, food intake and energy expenditure have resulted in substantial interest in FGF21 as a potential treatment for obesity and metabolic syndrome." (PMID 28652585, 2017). "In the past decades, the bulk of scientific research focused on the mechanism of FGF21 regulating glucose and lipid metabolism in obesity and diabetes." (PMID 29109955, 2017).
Obesity (continued). "As reported, in obesity and diabetes, markedly elevated circulating FGF21 level has led to an FGF21-resistant state." (PMID 29109955, 2017). "We suggest that Creb/Crtc2 negatively regulates the Sirt1/Pparα/Fgf21 axis via the induction of miR-34a under diet-induced obesity and insulin-resistant conditions." (PMID 29192248, 2017). "Patients with obesity and type 2 diabetes receiving LY2405319 (LY), a variant of FGF21, produced significant improvements in dyslipidemia." (PMID 28225059, 2017). "Previous studies have demonstrated that FGF21 mRNA level was markedly increased in the liver and adipose tissue of db/db or diet-induced obesity mice." (PMID 28466020, 2017). "MHY2013 elevated blood FGF21 and adiponectin and increased adipose tissue browning, thereby contributing to improved obesity-induced insulin resistance, hepatic steatosis, and dyslipidemia without affecting body weight." (PMID 28129657, 2017). "Fibroblast growth factor 21 (FGF21), liver-derived hormone, exerts diverse metabolic effects, being considered for clinical application to treat obesity and diabetes." (PMID 28374855, 2017). "Despite the beneficial effect of FGF21 found in animal studies, circulating FGF21 levels in human are elevated in obesity, metabolic syndrome, type 2 diabetes and coronary artery disease." (PMID 28698650, 2017). "The elevated FGF21 levels during obesity have led to the postulation that obesity is a “FGF21-resistant state”." (PMID 28580290, 2017). "FGF21 has been considered a promising intervention target for metabolic diseases, including fatty liver, obesity, and diabetes due to its insulin-sensitizing and thermogenesis-inducing effects." (PMID 28129657, 2017). "BAT releases fibroblast growth factor 21 (FGF21), a peptide hormone that can alleviate obesity and diabetes in animal experiments, and which increases insulin sensitivity and reduces gluconeogenesis in the liver." (PMID 28288167, 2017). "Transgenic mice with overexpression of FGF21 are resistant to diet-induced obesity and metabolic disturbance." (PMID 28466020, 2017). "As compared to CK-18, FGF-21 improves insulin sensitivity and insulin resistance in obesity animal models." (PMID 28326329, 2017). "Obese monkeys display high levels of FGF21 and reduced levels of β-klotho in adipose tissue, whereas monkeys that maintained normal levels of β-klotho are protected against obesity." (PMID 28770320, 2017). "In order to test if FGF21 is sufficient to inhibit hyperglycaemia in a model of polygenetic obesity and type 2 diabetes we used NZO mice on a specific dietary regimen that leads to the onset of diabetes within 1 week." (PMID 28770320, 2017). "Our results suggest that Sp1 regulates liver and adipose tissue FGF21 expression in normal physiological states and contributes to the obesity-induced FGF21 upregulation in adipose tissue and hepatic FGF21 upregulation in hepatocarcinogenesis." (PMID 28466020, 2017). "Circulating FGF21 levels are elevated in various metabolic disease states, such as obesity, insulin resistance, and type 2 diabetes mellitus." (PMID 28582462, 2017). "We therefore further tested the potential role of FEN in regulating hepatic Fgf21 in mouse models of diet and genetically-induced obesity and in wild-type animals." (PMID 28256636, 2017). "Mice deficient in skeletal muscle autophagy promote whole-body energy metabolism and confer resistance to obesity through Fgf21 expression, similar to that seen in our TG mice." (PMID 26487695, 2016). "To investigate the mechanism by which metformin regulates obesity, we analyzed the expression of CoxIV and FGF21 using confocal staining." (PMID 27057099, 2016). "In this study, we detected serum FGF21 levels in obese patients and patients with obesity-related AN." (PMID 27190511, 2016). "Our results indicated that skeletal muscle–secreted FGF21 was responsible for resistance to HFD-induced obesity." (PMID 26487695, 2016).